JAK2 (Janus kinase 2)
Diseases named in the same sentence as JAK2 in open-access papers (continued):
Sharing a sentence is not in itself a finding about the gene and the disease.
myeloproliferative neoplasm (continued). "Moreover, thrombocytopenia is a common side effect in myeloproliferative neoplasm patients with JAK1/2 inhibitor therapy, which target in hematopoietic stem and precursor cell mutant JAK2-V617F as well as wile-type JAK2." (PMID 33722280, 2021). "In this subsection, we used MULAN to analyze scSeq data from JAK2-negative myeloproliferative neoplasm and from lymphoblastic leukemia." (PMID 33253159, 2020). "The models were compared for the perfect phylogeny TPF and the two most probable recurrence trees TFRG and TASNS for the JAK2-negative myeloproliferative neoplasm, as well as for the trees produced by SCITE for lymphoblastic leukemia datasets." (PMID 33253159, 2020). "Fedratinib is currently approved by the FDA for use in myeloproliferative neoplasms that take advantage of the JAK2 pathway, such as polycythemia vera; however, it has not been tested in the setting of viral syndromes yet." (PMID 32707537, 2020). "In addition, JAK2 is the overlapping gene, and disregulation of the IL6/JAK2/STAT3 signalling pathways can lead to increased cellular proliferation and myeloproliferative neoplasms of hematopoietic stem cells." (PMID 33126852, 2020). "On the other hand, somatic mutations in the endoplasmic reticulum chaperone gene (CALR) are detectable in a majority of myeloproliferative neoplasms (MPN) patients with non-mutated JAK2 and in a small proportion of MPN somatic mutations in the MPL gene have been also reported." (PMID 31064135, 2019). "Calreticulin (CALR) gene mutations are currently recommended as biomarkers in diagnosis of patients with myeloproliferative neoplasms (MPN) with Jak2 V617F negative phenotype." (PMID 31248375, 2019). "For example, more than 90% of the non-leukemic classical myeloproliferative neoplasms (MPNs) are clearly driven by abnormal JAK2 activation, especially the cytokine receptor/JAK2 pathways and their downstream effectors." (PMID 29946544, 2018). "According to the classification of the World Health Organization (WHO) in 2008, JAK2 positivity was accepted to be one of the major criteria in the diagnosis of Ph-negative myeloproliferative disorders." (PMID 29732039, 2018). "BCR-ABL1 negative myeloproliferative neoplasms (MPNs) are known to contain alterations of the tyrosine kinase JAK2 (located on 9p24) that result in constitutive activation of the encoded protein." (PMID 25789185, 2015). "Recently, a splicing isoform of JAK2, lacking exon 14 (JAK2Δ14) was described in patients affected by myeloproliferative diseases." (PMID 25617626, 2015). "Pacritinib, a dual JAK2 and FLT3 inhibitor has showed significant promise in early phase trials with limited haematologic toxicity and is currently in Phase III clinical trials for myeloproliferative disorders." (PMID 25656053, 2015). "Mutations in JAK2, MPL and CALR are highly relevant to the Philadelphia chromosome (Ph)-negative myeloproliferative neoplasms (MPNs)." (PMID 25023898, 2014). "A multiplex snapback primer system was developed for the simultaneous detection of JAK2 V617F and MPL W515L/K mutations in Philadelphia chromosome- (Ph-) negative myeloproliferative neoplasms (MPNs)." (PMID 24729973, 2014). "Although it is evident that JAK2 acts as an oncogene in both myeloproliferative disorders and some solid tumors, no direct involvement of JAK2 in cancer migration, invasion or metastasis has been reported." (PMID 25055044, 2014). "Current JAK2 inhibitors used for myeloproliferative neoplasms (MPN) treatment are not specific enough to selectively suppress aberrant JAK2 signalling and preserve physiological JAK2 signalling." (PMID 24251790, 2013). "The chronic myeloproliferative neoplasms (MPN), which include polycythemia vera (PV), essential thrombocythemia (ET) and primary myelofibrosis (PMF), are characterized by a V617F point mutation in the exon 14 of Janus Kinase 2 (JAK2) that occurs in 95% of PV and 60% of ET or PMF patients." (PMID 23382981, 2013).
myeloproliferative neoplasm (continued). "In another study including 50 myeloproliferative disease cases, of which 26 were JAK2 V617F negative, it was detected that the age and Hb level were higher in patient bearing the mutation, but on the other hand, PLT count was significantly lower." (PMID 22997499, 2012). "Moreover, the dual inhibition of JAK2 and FLT3 could also provide therapeutic option in the treatment of acute myelogenous leukemia and myeloproliferative neoplasms." (PMID 35631587, 2022). "These age-related mutations found in genes such as DNMT3A, TET2, JAK2, and ASXL1, although they are also found in myeloid neoplasms including myelodysplastic syndromes, acute myeloid leukemia, and myeloproliferative neoplasms, in CHIP, they do not cause alterations in peripheral blood counts." (PMID 34988471, 2021). "It is especially visible for the JAK2-negative myeloproliferative neoplasm." (PMID 33253159, 2020). "Janus kinase 2 (JAK2) and signal transducer and activator of transcription-5 (STAT5) play a key role in the pathogenesis of myeloproliferative neoplasms (MPN)." (PMID 32326377, 2020). "Furthermore, it is not certain whether our dosage was appropriate for inhibiting JAK2 in HL and PMBCL tumor cells because we used the dosage recommended for myeloproliferative neoplasms." (PMID 31707975, 2019). "Hence, we examined a cohort of 123 myeloproliferative neoplasm (MPN) patients without BCR-ABL1 rearrangement and additional ET patients (n=96) for coexistence of JAK2 and CALR mutations." (PMID 27486987, 2016). "A somatic point mutation in the JAK2 gene, 1849G>T, which changes amino acid residue 617 of the kinase from valine to phenylalanine (termed JAK2 V617F), has been identified by various studies in a substantial number of Philadelphia chromosome-negative myeloproliferative neoplasm (Ph-MPN) patients." (PMID 25013507, 2014). "Related studies have found that AML progression from JAK2-mutant (JAK2-mut) myeloproliferative neoplasms (MPN) (after MPN AML) has a poor prognosis, and the BCL-XL is overexpressed in the cells of patients with JAK2-mut MPN." (PMID 39169396, 2024). "Furthermore, it has been reported that the JAK2/STAT3 pathway participates in the protective effect of erythropoietin (EPO) in subarachnoid hemorrhage (SAH); also, JAK2 and telomerase have a combination effect in the treatment of myeloproliferative neoplasms (MPNs)." (PMID 34585328, 2021). "JAK2/STAT signaling participates in the Ph-negative myeloproliferative neoplasms (MPN) pathophysiology and has been targeted by ruxolitinib, a JAK1/2 inhibitor." (PMID 31289316, 2019). "Thus, aberrant activation of Jak2 by the V617F mutation enhances survival and proliferation of hematopoietic cells and plays a crucial role in pathogenesis the Philadelphia chromosome (Ph)-negative myeloproliferative neoplasms (MPN), such as polycythemia vera and essential thrombocythemia." (PMID 27286446, 2016). "However, allogeneic hematopoietic cell transplantation (HCT) is the only curative therapy for MF since ruxolitinib does not eliminate the myeloproliferative neoplasm (MPN) clone, reduce JAK2 V617F allele burden, or regress bone marrow fibrosis in most patients." (PMID 27840748, 2016). "While JAK2 translocations are not common in lymphoblastic leukemia, it is clear that newly developed small molecular JAK2 inhibitors such as TG101348 and TG10129 developed by TargetGen, Inc. show promising results in blocking the action of mutated JAK2 in myeloproliferative disorders." (PMID 24274401, 2013). "It is worth mentioning that the immunoglobulin E levels were also elevated, but further investigations including myeloproliferative neoplasm (MPN) fluorescence in situ hybridization (FISH), flow cytometry, and Janus kinase 2 (JAK2) V617F cascade were negative." (PMID 38966441, 2024).
myeloproliferative neoplasm (continued). "Philadelphia chromosome-negative myeloproliferative neoplasms (MPN) are clonal hematopoietic stem cell disorders and, based on activated JAK2 signaling, present with an excessive output of mature blood cells of one or more myeloid lineages." (PMID 35215273, 2022). "JAK2, CALR, and MPL genes play pivotal roles in the pathogenesis of BCR-ABL negative myeloproliferative neoplasms." (PMID 33936230, 2021). "Activation of the JAK2/STAT1 pathway, not necessarily through phosphorylated STAT1, is related to myeloproliferative neoplasms, and blockade of IFNγ reduced melanomagenesis." (PMID 24065129, 2013). "Detection of the JAK2 V617F variant in patients with Philadelphia-negative myeloproliferative neoplasms (MPNs), including polycythemia vera (PV), essential thrombocythemia (ET), and primary myelofibrosis (PMF) has changed the MPN molecular diagnostics routine over recent years." (PMID 32150880, 2020).
myelofibrosis (342 papers, 2006 to 2026). A partial or complete replacement of the bone marrow stroma by fibrous tissue. "Median age was 62 years; most cases evolved from myelofibrosis, and JAK2 was the predominant driver mutation." (PMID 41991667, 2026). "Molecular analysis identified a JAK2 V617F mutation (variant allele fraction 40%), confirming PV with progression toward myelofibrosis." (PMID 41993099, 2026). "As this is not a hematopathology report, detailed descriptions are omitted, but the abnormal white blood cell and platelet counts in this patient appeared to be caused by myelofibrosis caused by the JAK2 mutation." (PMID 39897264, 2025). "This case describes a patient with early-stage myelofibrosis, with JAK2 V617F mutation, and Grade 1 reticulin fibrosis on bone marrow biopsy." (PMID 41141709, 2025). "The risk of arterial and venous thrombosis, and the transformation to myelofibrosis (post-PV MF) and acute leukemia, is directly related to JAK2 V617V mutation burden." (PMID 40507313, 2025). "Elevated JAK2 V617F VAFs are correlated with increased leukocyte counts, higher risk of transformation to myelofibrosis, and a greater likelihood of developing splenomegaly." (PMID 41226376, 2025). "Fedratinib is an oral Janus kinase 2-selective inhibitor for the treatment of adult patients with intermediate-2 or high-risk myelofibrosis; however, some patients have difficulty with oral dosing." (PMID 37955741, 2024). "The case we report not only exhibited grade 2 myelofibrosis but also harbored a JAK2 V617F mutation with a high VAF, thereby confirming a diagnosis of PMF." (PMID 39224801, 2024). "Acquisition of Ras-activating mutations contributed resistance against JAK2 inhibitors also in myelofibrosis patients." (PMID 39104388, 2024). "The landscape of myelofibrosis (MF) has changed since the discovery of the JAK2 V617F mutation and subsequent development of JAK inhibitors (JAKis)." (PMID 39400853, 2024). "In AML secondary to MPNs, the most common mutation is JAK2 V617F, which accounts for 98% of polycythemia vera (PV) and 55–60% of essential thrombocythemia (ET) and myelofibrosis cases." (PMID 39590121, 2024). "Further insights into the interplay between JAK1 selectivity and infection risk are provided by real-life data on the employment of a novel JAK2-selective drug, fedratinib, used in the therapy of intermediate or high-risk, primary or secondary myelofibrosis." (PMID 39124690, 2024). "A bone marrow biopsy demonstrated increased megakaryocytes and granulocytes, and genetic testing identified the presence of the Janus kinase 2 V617F (JAK2 V617F) mutation, leading to a diagnosis of pre-primary myelofibrosis (pre-PMF)." (PMID 39395952, 2024). "A previous study found that patients with higher JAK2 V617F burden (> 50% variant allele frequency) have a higher myelofibrosis transformation rate than patients with < 50% frequency." (PMID 38951434, 2024). "Myelofibrosis is a myeloproliferative neoplasm associated with mutations in the cytoplasmic tyrosine kinase Janus kinase (JAK) 2, and dysregulation of the JAK/signal transducer and activator of transcription pathway." (PMID 37955741, 2024). "Two JAK2 inhibitors, ruxolitinib and fedratinib, have been approved for patients with intermediate and high-risk myelofibrosis." (PMID 39091915, 2024). "It seems that both CALR and JAK2 mutations have a similar risk of transformation to post-ET myelofibrosis." (PMID 37745842, 2023). "Management strategies for PMF have evolved over the last two decades, including approval of ruxolitinib as the first Janus kinase 1 (JAK1)/JAK2 inhibitor for patients with intermediate or high-risk myelofibrosis." (PMID 36641455, 2023). "Lestaurtinib was also tested in patients with JAK2 mutations and myelofibrosis, who responded to treatment in some cases." (PMID 37404750, 2023). "Myelofibrosis patients frequently carry driver mutations in either JAK2 or Calreticulin (CALR) and have limited therapeutic options." (PMID 37828014, 2023).
myelofibrosis (continued). "JAK2 mutations, specifically V617F, are common in myelofibrosis (35–57%), ubiquitous in polycythemia vera, occurring in 96–99% of patients, and are also the most commonly mutated gene in essential thrombocythemia (50–60%)." (PMID 37760623, 2023). "Among the other factors, sOA was univariately associated with the presence of JAK2 mutation, myelofibrosis phenotype, older age, higher body weight, and higher MPN-SAF score (p < 0.050 for all analyses)." (PMID 37374170, 2023). "We included 37 relapsed patients of whom 22 patients had primary myelofibrosis (60%) and 30 patients had JAK2 driver mutation genotype (81%)." (PMID 37404772, 2023). "The primary driver mutations in myelofibrosis are well-established and mainly include JAK2, CALR, and MPL mutations." (PMID 37760623, 2023). "A third patient (UPN126), previously diagnosed with primary myelofibrosis associated with a JAK2-mutation, transformed to a secondary AML 2 years after the initial diagnosis." (PMID 35821208, 2022). "Ruxolitinib (Jakafi) is another JAK1/JAK2 inhibitor approved for the treatment of intermediate and high-risk myelofibrosis." (PMID 35626663, 2022). "Ruxolitinib has been successfully used in treating myelofibrosis and polycythemia vera patients harboring JAK2 VS17F mutations that are resistant to HU therapy." (PMID 35949766, 2022). "CXCL12/CXCR4 pathway is activated by oncogenic JAK2, which frequently suffers activating mutations in primary myelofibrosis." (PMID 35356507, 2022). "Fedratinib is an orally administered Janus kinase (JAK) 2–selective inhibitor for the treatment of adult patients with intermediate-2 or high-risk primary or secondary myelofibrosis." (PMID 36001108, 2022). "MPL mutations have been observed in a few cases of JAK2 V617F positive PV and post-PV myelofibrosis, supporting previous data reporting that MPL mutations rarely occur in PV." (PMID 35456443, 2022). "Ruxolitinib is an approved drug for polycythemia vera and myelofibrosis caused by activated JAK2 mutations." (PMID 36295656, 2022). "Ruxolitinib is not selective for the mutated JAK2 and can therefore be used in both JAK2-mutated and JAK2-unmutated myelofibrosis." (PMID 36479156, 2022). "The CXCL12/CXCR4 pathway can be induced by oncogenic JAK2, which frequently suffers activating mutations in primary myelofibrosis, and JAK2 inhibition can reduce the chemotaxis of hematopoietic cells isolated from primary myelofibrosis." (PMID 35356507, 2022). "Osteoclasts derived from individuals with myelofibrosis harboring JAK2 activating mutations have impaired osteolytic capacity, implicating JAK2 with osteoclast dysfunction." (PMID 33682794, 2021). "In patients with myelofibrosis, the JAK2 mutation is associated with dysregulation of the Bcl-2 proteins." (PMID 34667663, 2021). "Collectively, these human data suggest that point mutations in the pseudokinase domain of JAK1 are critical to pathological processes, similarly to the well-known JAK2 V617F mutation found in polycythaemia vera, myelofibrosis, and essential thrombocythemia." (PMID 35046931, 2021). "Ruxolitinib, a selective Jak2 inhibitor, has been used for the clinical treatment of primary myelofibrosis with the JAK2 V617F mutation." (PMID 34588425, 2021). "Evidence for NFκB signaling hyperactivation was also observed in MPL W515L model mice, and in Jak2 V617F model mice with loss of Dnmt3a, which showed a myelofibrosis-like phenotype." (PMID 34140953, 2021). "JAK2 inhibitors are currently approved for intermediate or high-risk myelofibrosis and for polycythemia vera resistant to hydroxyurea." (PMID 34680226, 2021). "Myelofibrosis (MF) is a clonal disorder of hemopoietic stem/progenitor cells (HSPCs) with high prevalence in elderly patients and mutations in three driver genes (JAK2, MPL, or CALR)." (PMID 33522952, 2021).